PRAMEF19 (PRAME family member 19)
Synonyms: OTTHUMG00000007919
Tractability: No criterion of Open Targets' tractability assessment is met for any kind of drug.
Gene: Protein-coding gene on chromosome 1 (13,368,431 to 13,371,947, reverse strand). Ensembl gene ENSG00000204480.
Gene Ontology:
Molecular function: ubiquitin-like ligase-substrate adaptor activity
Biological process: proteasome-mediated ubiquitin-dependent protein catabolic process; negative regulation of apoptotic process; negative regulation of cell differentiation; negative regulation of DNA-templated transcription; positive regulation of cell population proliferation
Cellular component: Cul2-RING ubiquitin ligase complex; cytoplasm
Genetic constraint (gnomAD): Loss-of-function variants: 21 observed, 30.62 expected, observed/expected ratio (o/e) 0.69, 90% interval 0.49 to 0.99. The upper end of that interval is the gene's LOEUF score, 0.99, which puts it in group 4 of 6, group 1 being the genes least tolerant of losing a copy. Missense variants: 481 observed, 553.83 expected, observed/expected ratio (o/e) 0.87, 90% interval 0.81 to 0.94. Synonymous variants: 179 observed, 216.58 expected, observed/expected ratio (o/e) 0.83, 90% interval 0.73 to 0.94.
Homologues: Orthologues: chimpanzee PRAMEF19 (96% identical), mouse Pramel12 (44% identical), rat Pramef8 (43% identical), rat LOC120103107 (42% identical), mouse Pramel13 (41% identical), mouse Pramel21 (41% identical), mouse Pramel11 (40% identical), mouse Pramel36 (40% identical), mouse Pramel46 (40% identical), mouse Pramel49 (40% identical), mouse Pramel24 (40% identical), mouse Pramel32 (40% identical), and 79 more. Paralogues in human: PRAMEF18 (92% identical), PRAMEF1 (61% identical), PRAMEF10 (61% identical), PRAMEF33 (61% identical), PRAMEF17 (61% identical), PRAMEF14 (60% identical), PRAMEF2 (60% identical), PRAMEF13 (60% identical), PRAMEF12 (53% identical), PRAMEF20 (53% identical), PRAMEF8 (51% identical), PRAMEF7 (50% identical), and 12 more.